UHRF1 (ubiquitin like with PHD and ring finger domains 1)
Diseases named in the same sentence as UHRF1 in open-access papers (continued):
Sharing a sentence is not in itself a finding about the gene and the disease.
colon cancer (continued). "Studies have shown that UHRF1 plays an important role in the development of various cancers such as lung adenocarcinoma, bile duct cancer, kidney cell cancer, prostate cancer, colon cancer, and pancreatic cancer." (PMID 35656341, 2022). "The fact that DNMT3A and HDAC3 are degraded in methylation-sensitive colon cancer cells in part via blocking their connection with the E3 ubiquitin ligase UHRF1 could explain this decrease in expression." (PMID 35327559, 2022). "Acetylation of UHRF1 4K residues by TIP60 is important for colon cancer cell growth." (PMID 35951156, 2022). "Studies to find other TSGs regulated by UHRF1 in colon cancer have been continued, our findings could contribute to reveal the oncogenic function of UHRF1." (PMID 35951156, 2022). "Through a series of experiments to identify proteins that may be related to UPAT, researchers found that UPAT can interfere with the ubiquitination and degradation of UHRF1 in colon tumors through the proteasome, thereby maintaining the stability of UHRF1." (PMID 34803512, 2021). "LncRNA UPAT interacts with and stabilizes UHRF1 by blocking the β-transducin repeat-containing protein (β-TrCP)-induced ubiquitination of UHRF1 to promote Stearoyl-CoA desaturase 1 and Sprouty 4, of which is necessary to maintain colon cancer cell survival." (PMID 33246471, 2020). "The SRA domain supports UHRF1 oncogenic activity in colon cancer cells, highlighting that UHRF1 SRA antagonism could be a cancer therapeutic strategy." (PMID 31481468, 2019). "We used mouse CMT93 cells, a colon cancer cell line that has prominent heterochromatin sites as evidenced by DAPI staining, to test our hypothesis that MBD4 and UHRF1 might associate with each other at heterochromatin sites." (PMID 25358258, 2015). "Whether UHRF1 acetylation by TIP60 can induce cell proliferation in colon cancer cells." (PMID 35951156, 2022). "Colon cancer is a paradigm in which the roles of DNA methylation, DNMT1, and UHRF1 have been extensively investigated." (PMID 35625988, 2022). "Our data demonstrated that hinokitiol decreased DNMT1 and UHRF1 expression and increased the level of TET1 in colon cancer cell line HCT-116." (PMID 28241740, 2017). "With transient transfection of UHRF1 WT and 4KR, the effects of UHRF1 4KR mutant on Jun dimerization protein 2 (JDP2) gene expression, cell proliferation and cell cycle were investigated by RT-qPCR and FACS analysis in shUHRF1 colon cancer cell line." (PMID 35951156, 2022). "As expected, no intestinal and colon tumors were observed in Apc+/+ mice for Uhrf1+/+, Uhrf1+/ki and Uhrf1ki/ki genetic background (data not shown)." (PMID 33947834, 2021). "They found that the interaction of UHRF1 with UHRF1BP1 may lead to relocation of UHRF1, while overexpression of UHRF1BP1 appeared to inhibit cell growth in colon cancer cell lines, which indicated that UHRF1BP1 could act as a tumor suppressor." (PMID 32117775, 2020). "Overexpression of UHRF1 was also observed in LoVo, DLD1, SW480 and SW620 colon cancer cell lines." (PMID 28881702, 2017). "UHRF1 ubiquitin ligase activity was needed to support DNA methylation maintenance in low CpG density regions of the genome in both HCT116 and RKO colon cancer cell lines, consistent with the hypothesis of histone ubiquitination functioning as a bookmark for low-density CpG methylation." (PMID 39607687, 2024).
bladder cancer (20 papers, 2009 to 2024). "UHRF1 has also been described as a ‘novel’ diagnostic and prognostic marker for the bladder cancer, which is the second most common cancer of the urinary system." (PMID 28881702, 2017). "Associations of UHRF1 level with clinicopathologic characteristics in 47 patients with bladder cancer." (PMID 25272010, 2014). "Overexpression of UHRF1 in bladder cancer is also correlated with increased risk of cancer progression after transurethral resection." (PMID 25272010, 2014). "Overexpression of UHRF1 in bladder cancer was associated with increased risk of progression after transurethral resection." (PMID 19491893, 2009). "The UHRF1 can be detected in tissue samples and urine sediment from patients with bladder cancer, and thus can be a diagnostic and/or prognostic marker." (PMID 19491893, 2009). "Moreover, high tumoral expression of UHRF1 is associated with poor prognosis of several cancer types, including hepatocellular carcinoma, pancreatic, breast, and bladder cancer." (PMID 36077796, 2022). "At the molecular level, the epigenetic silencing of KISS1 in bladder cancer is due to the upregulation of Ubiquitin-like with PHD and RING finger domains 1 (UHRF1)." (PMID 31336647, 2019). "Studies have also shown that overexpression of UHRF1 can inhibit the expression of KISS1 mRNA in bladder cancer." (PMID 31803739, 2019). "For example, miR-145-3p and -5p inhibit the aggressiveness of bladder cancer cells by suppressing UHRF1 and function as tumor suppressor in lung squamous cell carcinoma through down-regulation of MTDH." (PMID 31262974, 2019). "The expression of UHRF1 increases in multiple kinds of cancers, including bladder cancer, colorectal cancer and gastric cancer." (PMID 30352833, 2018). "UHRF1 expression enhances in nasopharyngeal carcinoma tissues and acted a tumor inductor in bladder cancer." (PMID 30352833, 2018). "Our results are in accordance with some of the previous studies about potential usefulness of UHRF1 overexpression as a prognostic prediction factor in urinary bladder cancer." (PMID 28128913, 2017). "Other studies reported similar overexpression of UHRF1 in bladder cancers and in invasive cell lines, such as 253J, T24, KU7, along with silencing of tumor suppressor genes e.g., KISS1 and RGS2." (PMID 28881702, 2017). "In this study, RT-PCR analysis revealed that the mean UHRF1 gene mRNA expression values in bladder cancer patients group were approximately 2.5 times higher than in the normal urothelium control group." (PMID 28128913, 2017). "The result of this study indicates that UHRF1 gene expression levels correlates with the high grade urinary bladder cancer, as well as with the muscle invasive stage." (PMID 28128913, 2017). "Altogether, these studies emphasize UHRF1 as an attractive biomarker and therapeutic target for bladder cancers." (PMID 28881702, 2017). "In the same way, the tumor suppressor gene, miR-145-5p and 145-3p as well, were shown to down-regulate UHRF1 in bladder cancer, with subsequent apoptosis by targeting genes such as BIRC5 and CENPF." (PMID 27839516, 2016). "UHRF1 levels are relatively higher with concurrent low levels of KiSS1 in invasive bladder cancer cell lines." (PMID 25272010, 2014). "Our results revealed that UHRF1 expression is upregulated in primary tumors that subsequently metastasized, and overexpression of UHRF1 promotes bladder cancer cell invasion by epigenetic silencing of KiSS1." (PMID 25272010, 2014). "UHRF1 decreases KiSS1 expression by increasing the methylation of CpG nucleotides of KiSS, and downregulation of KiSS1 promotes bladder cancer cell invasion." (PMID 25272010, 2014). "Forced expression of UHRF1 promotes bladder cancer cell invasion, whereas UHRF1 knockdown decreases cell invasion." (PMID 25272010, 2014).
bladder cancer (continued). "Our data showed that upregulated UHRF1 contributes to bladder cancer cell invasion by epigenetic silencing of KiSS1." (PMID 25272010, 2014). "In the present study, we found that the expression levels of UHRF1 are significantly increased in most bladder cancer tissues compared with adjacent normal controls." (PMID 25272010, 2014). "We also found that the UHRF1 levels are relatively higher in invasive bladder cancer cell lines than those in the noninvasive ones." (PMID 25272010, 2014). "UHRF1 is a very important regulator of DNA methylation, and aberrant DNA methylation is a frequent epigenetic event in bladder cancer." (PMID 25272010, 2014). "But the increased levels of UHRF1 in kidney cancer were less significant compared with those in bladder cancer." (PMID 19491893, 2009). "Similarly, a promoter hypermethylation of G-protein signaling 2 (RGS2) gene by UHRF1 resulted in gene suppression and enhanced carcinogenesis in bladder cancer." (PMID 36077796, 2022). "UHRF1 levels evaluated by qRT-PCR or immunohistochemistry based detection methods in surgical sections showed UHRF1 as a specific and sensitive biomarker for bladder cancer." (PMID 28881702, 2017). "Furthermore, it was demonstrated that the upregulated UHRF1 promotes bladder cancer cell invasion by epigenetic silencing of KiSS1 metastasis suppressor gene coding for kisspeptin." (PMID 28128913, 2017). "This suggests UHRF1 as an independent prognostic marker for the bladder cancers." (PMID 28881702, 2017). "Determination of UHRF1 gene expression could have a potential to be used as a sensitive molecular marker in patients with urinary bladder cancer." (PMID 28128913, 2017). "Interestingly, in this study UHRF1 was reported to be upregulated in bladder cancer clinical specimens and to promote anti-apoptotic effects through regulation of several oncogenic genes." (PMID 27839516, 2016). "Despite these intriguing findings, little is known about whether UHRF1 increases bladder cancer cell invasion by epigenetic silencing of KiSS1." (PMID 25272010, 2014). "The role of UHRF1 in regulating bladder cancer metastasis was evaluated in bladder cancer cell." (PMID 25272010, 2014). "To assess whether UHRF1 regulates bladder cancer metastasis, we first examined UHRF1 expression in bladder cancer cell lines and cancer tissues." (PMID 25272010, 2014). "Here we investigated whether UHRF1 regulates bladder cancer cell invasion by epigenetic silencing of KiSS1." (PMID 25272010, 2014). "We found that UHRF1 levels are upregulated in most clinical specimens of bladder cancer when compared with paired normal tissues, and UHRF1 expression levels are significantly increased in primary tumors that subsequently metastasized compared with non-metastatic tumors." (PMID 25272010, 2014). "In the study, we tested whether UHRF1/KiSS1 represents a novel pathway regulating bladder cancer cell invasion." (PMID 25272010, 2014). "Significant overexpression of UHRF1 was observed in bladder cancer." (PMID 19491893, 2009). "Determination of expression of UHRF1 gene could have a potential to be used as a very sensitive molecular marker with a prospective value in clinicopathological evaluation and prognosis of patients with urinary bladder cancer." (PMID 28128913, 2017). "Finally, it was suggested that UHRF1 might be a useful prognostic marker for survival of bladder cancer patients." (PMID 27839516, 2016). "We therefore investigated whether UHRF1 promotes bladder cancer cell invasion by inhibiting KiSS1." (PMID 25272010, 2014). "In this study, we examined whether UHRF1 can be a novel molecular marker of bladder cancer." (PMID 19491893, 2009). "The UHRF1 was significantly overexpressed in bladder tumours (P<0.0001, Mann–Whitney's U-test), especially in 12 upper tract TCCs (P<0.0001, Kruskal–Wallis test): 10 percentile of the upper tract TCCs is higher than 50 percentile of the bladder-origin bladder cancers." (PMID 19491893, 2009).
bladder cancer (continued). "In human bladder cancer cells, MiR-124 competitively binds to the 3'UTR of UHRF1 mRNA, contributing to the reduction of UHRF1." (PMID 31772665, 2019). "For example, miR-145-3p and -5p cooperatively regulate cancer progression and aggressiveness of lung and bladder cancer by suppressing metadherin (MTDH) and ubiquitin-like with PHD and ring finger domains 1 (UHRF1), respectively." (PMID 31262974, 2019). "Previous study indicated that UHRF1 is overexpressed in a variety of tumor tissues such as gastric cancer, bladder cancer and HCC, and UHRF1 overexpression is negatively correlated with prognosis of HCC patients." (PMID 28060737, 2017). "We then assayed the expression level of UHRF1 and KiSS1 in both invasive bladder cancer cell lines and noninvasive bladder cancer cell lines." (PMID 25272010, 2014). "In the result, UHRF1 was overexpressed more than twice in 86% of these bladder-cancer cases (data not shown), indicating that overexpression of UHRF1 in bladder cancer is probably common worldwide." (PMID 19491893, 2009).
gastric cancer (18 papers, 2014 to 2025). A primary or metastatic malignant neoplasm involving the stomach. "Moreover, elevated levels of UHRF1 in the blood of breast and gastric cancer patients has been shown to provide diagnostic and prognostic value as an independent biomarker." (PMID 31245293, 2019). "In various cancers, including bladder, colorectal, renal, lung, and gastric cancers, the tumor-suppressive regulation of UHRF1 by miRNAs has been reported." (PMID 41373864, 2025). "Inversely, the downregulation of UHRF1 in MKN45 gastric cancer cells induced promoter demethylation and reduced cellular proliferation through the activation of different tumor suppressor genes." (PMID 36077796, 2022). "Several studies sought to reveal the function of UHRF1 on TSGs in multiple cancer cells such as lung and gastric cancer and these TSGs were silenced though its promoter hypermethylation." (PMID 35951156, 2022). "Studies on UHRF1 gene in gastric cancer showed that it promoted the proliferation of gastric cancer cells." (PMID 33934516, 2021). "More significantly, the level of UHRF1 overexpression corresponded directly with the stage of gastric cancer, being highest in stage IV and grade III." (PMID 29899856, 2018). "UHRF1 DNA levels measured in the serum of gastric cancer patients were substantially higher than those of healthy controls, and this finding is consistent with previous studies." (PMID 29899856, 2018). "In gastric cancer (GC), overexpression of UHRF1 was reported in metastatic tissue, while downregulation of UHRF1 suppressed gastric cancer invasion and metastasis." (PMID 29899856, 2018). "In 2013, a study reported high levels of UHRF1 in gastric cancers and explored miR-146a/b mediated regulation of UHRF1 as a novel therapeutic approach in preventing metastasis and treating such cancers." (PMID 28881702, 2017). "At the cellular level, overexpression of UHRF1 was observed in aggressive gastric cancer cell lines (GC9811-P and MKN28M), which has been suggested to enhance the proliferating capacity of these cells." (PMID 28881702, 2017). "Consistently, with this notion, same authors further explored the prognostic value of UHRF1 expression in a study including 238 gastric cancer patients." (PMID 28881702, 2017). "In addition, UHRF1 can inhibit cell apoptosis through the ROS-related signaling pathway in gastric cancer, and UHRF1 was found to enhance the invasive ability of tumor cells through the Keap1-Nrf2 pathway in pancreatic cancer." (PMID 31803739, 2019). "Results from both in vitro and in vivo studies, confirmed that UHRF1 downregulation could suppress the development of gastric cancer." (PMID 29899856, 2018). "For example, gene UHRF1 plays a significant role in the development of gastric cancer." (PMID 30597923, 2018). "Interestingly, the miR-146a-UHRF1 regulation has been shown as a key event in the metastatic progression in gastric cancer." (PMID 26859141, 2016). "UHRF1 overexpression has been reported to correlate with unfavorable prognosis in many cancers, including breast, lung, colorectal, prostate, bladder, and gastric cancer." (PMID 27507047, 2016). "In accordance with this, enhanced UHRF1 expression was also reported in gastric cancer (GC), and correlated with tumor progression." (PMID 27839516, 2016). "UHRF1 is overexpressed in colorectal cancer (CRC), non-small cell lung cancer (NSCLC) and gastric cancer." (PMID 29932172, 2018). "It is also notable that UHRF1 regulates other TSG as observed with CDX2, CDKN2A, RUNX3, FOXO4, PPARG, BRCA1 and PLM in gastric cancer, SOCS3 and 3OST2 in endometrial carcinoma, RB1 in Jurkat and osteosarcoma cells, as well as BRCA1 in cancer breast cell lines." (PMID 29932172, 2018). "Moreover, inoculation of UHRF1 depleted MKN45 gastric cancer cells into immunocompromised mice showed a marked reduction in tumor volume and weight compared to the control tumors where UHRF1 gene was not depleted." (PMID 31245293, 2019).
gastric cancer (continued). "Indeed, patients with higher expression of UHRF1 had a very low 5-year survival rate of 19% as compared to patients with negative (38%) or low expression of UHRF1 (30%) suggesting UHRF1 as a significant predictor of gastric cancer prognosis." (PMID 28881702, 2017). "It is also noteworthy that UHRF1 regulates a plethora of other TSGs among which RB1 especially in Jurkat and osteosarcoma cells, CDX2, CDKN2A, RUNX3, FOXO4, PPARG, BRCA1 and PLM, in gastric cancer, SOCS3 and 3OST2 in endometrial carcinoma as well as BRCA1 in cancer breast cell lines." (PMID 27839516, 2016).